CISAT (cobalt protoporphyrin induced and SFPQ associated RNA transcript)
Gene: Long non-coding RNA gene on chromosome 2 (240,372,912 to 240,387,764, reverse strand). Ensembl gene ENSG00000301884.
Diseases named in the same sentence as CISAT in open-access papers:
CISAT is named in the same sentence as 1 disease in open-access papers, as found by Europe PMC text mining. Sharing a sentence is not in itself a finding about the gene and the disease.
CISAT shares sentences with these, for which no sentence is quoted: heart disease (1 paper).